IL4 (interleukin 4)
Diseases named in the same sentence as IL4 in open-access papers (continued):
Sharing a sentence is not in itself a finding about the gene and the disease.
viral infection (continued). "SRLV viral infection induced M2 polarization of macrophages, which also exhibited high MR and DC-SIGN expression as observed upon IL-4 stimulation." (PMID 24070317, 2013). "The high production of IL-4 by the IL-4 (+33) TT genotype leads to a decrease in viral elimination by down regulation of the TH1 response, thereby affecting control of the viral infection." (PMID 22986179, 2012). "Interferon (IFNβ and IFNλ1) gene expression was increased after viral infection in healthy as well as asthmatic BECs, and treatment with IL-4 or IL-13 did not modulate this antiviral response." (PMID 40370530, 2025). "The obtained results may confirm the data on the role of IL-4 and IL-15 in mediating the development of specific CD8+ T cell memory during viral infections, which was confirmed by in vivo studies." (PMID 35632739, 2022). "These phenomena could be due to the fact that DVP-1 strengthened the organic immunity by stimulating the TLR4/MyD88/NF-κB signaling pathway by which more cytokines, such as IL-1β, IL-4, IL-6, and TNF-α, were generated and released before the viral infection." (PMID 36177044, 2022). "The leading contribution of MCs in response to viral infection might be in the context of the producing panel of mediators (amines, tryptase, chymase) and cytokines/chemokines (TNF-α, IL-4, IL-5, IL-6, IL-13, and IL-17)." (PMID 32185237, 2020). "As in regular viral infection, BTV12 activated monocytes normally and strongly, indicated by the TNF-α and IL-1β expressions, but activated the Th2 pathway poorly, indicated by the IL-4." (PMID 33375108, 2020). "Mannan, but not GalNac, specifically reduced virus infection of IL-4/IL-13 polarized murine pmacs and human MDMs, indicating that mannose binding receptors were responsible for mediating virus uptake." (PMID 31825972, 2019). "Thus, to our surprise M(IL-4) cells were very potent stimulators IFN-γ release from both GP33-41- and NP396-404-specific CD8+ T cells following viral infection." (PMID 29250063, 2017). "Up-regulation of Th1 cytokines (e.g. IL-12, INF-γ) and down-regulation of Th2 cytokines (e.g. IL-4, IL-10) and nitric oxide (NO) were the major targets to retain the th1/th2 balance corrupted by HCV viral infection and have an adequate anti-HCV cellular immune response." (PMID 27577059, 2016). "Unlike in human or mouse, in which IL4 is the major Th2 cytokine, the role of IL4 in pigs is not completely clear and its expression in vivo following viral infection is usually low or undetectable." (PMID 25479904, 2014). "Evidently, IL-4 produced by Th2 cells and natural killer T (NKT) cells is critical for antiviral CD8+ T-cell (IFN-γ- and TNF-α–secreting cell) functions and antibody development during early viral infections, all of which are essential for inhibiting the establishment of persistent virus infections." (PMID 37235332, 2023). "We showed that activated ILC2 increase viral infection of monocytes through a GM-CSF dependent, rather than an IL-4/13 dependent mechanism, and may contribute to systemic viral dissemination." (PMID 35869167, 2022). "Furthermore, DAE could also ameliorate viral infection through regulation of the levels of cytokines (IFN-γ, TNF-α, and IL-4) in PRV-infected mouse serum." (PMID 36699332, 2022). "This could be due to the extra IL-4/IL-13 we supplied to the cell culture, which may not be present in an in vivo setting during viral infection." (PMID 36129169, 2022). "We found that IL-4/IL-13 enhanced virus infection of pmacs by about 3 to 3.5-fold, regardless of whether PS liposomes were present suggesting these receptors do not mediate the IL-4/IL-13-enhanced infection." (PMID 31825972, 2019). "In conclusion, we provide evidence that helminth-driven type 2 immune responses drives TVM expansion through IL-4 which could in turn positively condition effector Ag-specific CD8+ T cells responses and significantly enhance the control of viral infection such as lytic gammaherpesvirus infections." (PMID 30375396, 2018).
viral infection (continued). "However, it has been shown that CD4+ T cell expression of Th2-type cytokines including IL-4 and IL-5 does not promote recovery from viral infection, but rather increases lung viral burdens." (PMID 25500584, 2014). "In vivo efficacy studies revealed that a single low dose of IL-2 or IL-4-bearing CYT-IVAC is superior at providing protection against lethal influenza challenge in a mouse model and provides a more balanced Th1/Th2 humoral immune response, similar to live virus infections." (PMID 19393093, 2009). "Bite-associated enhancement of infection was apparent in severe combined immunodeficiency (SCID) mice, which lack T and B cells, whereas classic Th1 or Th2 cytokines (e.g., IFN-γ, IL-4) could not be detected after mosquito biting of naive wild-type mice in the absence of virus infection." (PMID 27332734, 2016). "Even though IL-4/GM-CSF pathway of DC differentiation from peripheral blood monocytes is an efficient in vitro method to generate immature DCs, IL-4 is an anti-inflammatory cytokine and high levels of IL-4 are unlikely to be present during host response to acute virus infections." (PMID 23593001, 2013). "In our longitudinal study, we found that, in the absence of viral infection, CXCL10, IL-4, IL-13, CCL4, CCL5, CCL20 and CCL24 were each negatively associated with FVC." (PMID 30463560, 2018). "For example, in the absence of viral infection, CXCL10 mRNA, MDA5 mRNA, CXCL10, IL-4, IL-13, CCL4, CCL5, CCL20 and CCL24 were negatively associated with FVC." (PMID 30463560, 2018). "Although the TGFβ2 factor, recently recognized as a key factor in fibrosis induction, did not result upregulated by virus infection in HUVECs, other factors belonging to TGFβ superfamily were promoted in particular by HHV-6A, including GREM1 and INHBE, IL-4, IL-5, TNF, and MMP9." (PMID 31878218, 2019). "Indeed, in vivo reprogramming of Th2 cells to become “Th2+1′′ cells, expressing both IL-4 and IFN-γ has been previously reported in the context of viral infection, although not, to our knowledge, in the case of malignancy." (PMID 23717511, 2013). "Therefore, we were able to demonstrate that M(IL-4)-MΦ polarization does not negatively influence their ability to stimulate activation and release of IFN-γ from antigen-specific effector or memory CD8+ T cells after virus infection." (PMID 29250063, 2017).
autoimmune disease (126 papers, 2006 to 2025). A disorder resulting from loss of function or tissue destruction of an organ or multiple organs, arising from humoral or cellular immune responses of the individual to their own tissue constituents. "Conversely, the mRNA BNT162b2 vaccine is thought to indirectly promote the production of IL-4, IL-17, and IL-21 cytokines, which have associations with autoimmune disorders." (PMID 39203983, 2024). "A polymorphism (−C590T, rs2243250), in the promoter region of IL4 gene has been suggested as one of the genetic risk factors in autoimmune diseases." (PMID 37090926, 2023). "IL4, a critical anti-inflammatory cytokine and it has been implicated in the pathogenesis, activity and severity of various autoimmune diseases." (PMID 37090926, 2023). "Lymphocytes T and B are activated following BNT162b2 administration, and IL-2, IL-4, IL-17, and IL-21 are associated with autoimmune diseases, especially in genetically susceptible individuals." (PMID 37238357, 2023). "The mechanism of these suppressive effects against autoimmune diseases has also been suggested that vitamin D causes production of interleukin-4 (IL-4) and Transforming growth factor-beta (TGFB-1) which suppresses T-cell inflammatory activities." (PMID 33897222, 2020). "Although IL-4 and IL-13 are generally described as anti-inflammatory, both have been implicated in promoting antibody-mediated autoimmune diseases, such as MS and EAE." (PMID 31404142, 2019). "Another T helper subset characterized by the production of IL-4, IL-5 and IL-13, the Th2 subset can promote pathology of several different autoimmune diseases, particularly those which are associated with humoral immune responses." (PMID 27651750, 2016). "It has been suggested that the IL4 polymorphism (rs2243250) might be associated with genetic susceptibility to autoimmune diseases." (PMID 37047033, 2023). "This meta-analysis reported that IL4 rs2243250 polymorphism might be associated with genetic susceptibility of autoimmune diseases including RA and MS." (PMID 37090926, 2023). "Recent studies have implicated IL-4 and IL-13 in the development of various autoimmune diseases." (PMID 34831223, 2021). "In effect, the increased production of IL-4 seen in boatyard workers might confer upon them increased susceptibility to infection, allergic hypersensitivity, and/or autoimmune diseases dominated by Th2." (PMID 32823721, 2020). "High levels of ZAP70 expression and IL-4 secretion might be indicative of poor prognosis, and increased levels of IL-4 may be caused by infections and autoimmune diseases that accompany the disease." (PMID 26376785, 2016). "The overproduction of IL-4 is associated with inflammatory and autoimmune diseases." (PMID 26934574, 2016). "Despite its potential use for allergic and autoimmune diseases, its pleiotropic receptor binding complicates selective targeting of IL-4 signaling pathways." (PMID 40561016, 2025). "The antagonistic effect of IL-4 on Th1 polarization (a population characterized by IFN-γ production) suggests its potential as a therapeutic agent for autoimmune diseases." (PMID 40160814, 2025). "The lack of response from IFN- α, IL-17, and IL-4 was not completely unexpected, given the previously established evidence linking IFN-α to viral insult, IL-17 to autoimmune disease pathways, and IL-4 to allergic response." (PMID 41295728, 2025). "Although IL-17E is known to induce a Th2-mediated allergic response by stimulating IL-4, IL-5 and IL-13 production, several studies highlight its proinflammatory role in skin and autoimmune diseases." (PMID 38799435, 2024). "This is because IL-4 is thought to serve as a protection of the body from developing autoimmune diseases." (PMID 38397350, 2024). "For NULISAseq, IL4 levels were elevated in all four groups of autoimmune diseases (rheumatoid arthritis, Sjögren’s syndrome, systemic lupus erythematosus and ulcerative colitis)." (PMID 37945559, 2023).
autoimmune disease (continued). "In recent years, there has been a great interest in investigating the pathophysiologic role of IL-4 in several inflammatory and autoimmune diseases." (PMID 37763102, 2023). "IL-4 and IL-10 are key immunomodulatory cytokines that stimulate Th2 cell production while inhibiting Th1 response, hence limiting autoimmune disorders." (PMID 37893036, 2023). "Because of its protective effect in RA mouse models, IL-4 has the potential to be used as a treatment for autoimmune diseases." (PMID 37259429, 2023). "In this context, interleukin induction properties of mimic peptides were assessed using available web servers for IL-4, IL-6, and IL-13, as interleukins are involved in autoimmune disorders." (PMID 37513704, 2023). "Since there are prospects for use of IL-2 and IL-4 in the treatment of autoimmune diseases or infections, the respective contribution of T cell cytokine production to the pathogenesis of autoimmune diseases is still a matter of debate." (PMID 35155574, 2022). "Overall, we present a mouse model of an autoimmune disease induced directly by a bacterium that is dependent upon Siglec-1 and IL-4." (PMID 35442154, 2022). "IL-4 and IL-13 are anti-inflammatory cytokines, which play key roles in preventing inflammation and autoimmune diseases." (PMID 33953716, 2021). "The supporting function of the inflammatory process implemented by IL-6 can be counteracted using an opposing cytokine such as IL-4 both in the acute phase and, for example, for the contrast of the triggers of autoimmune diseases." (PMID 34067872, 2021). "Nevertheless, IL-4 is characterized by inducing type-2 immunity, and is essential in mediating wound-repair, suppression of autoimmune disease and maintenance of tissue homeostasis." (PMID 30704426, 2019). "One of the recent studies showed that IL-4 enhances IL-10 production by Th1 cells and ameliorate Th1 driven pathology in infectious, allergic, and autoimmune diseases." (PMID 31190704, 2019). "Although the pathological role of IL-4 and Th2 immune response in autoimmune development has been demonstrated in various autoimmune disorders, the role of IL-4 in autoimmunity remains controversial." (PMID 29184551, 2017). "IL-4 is the Th2 cytokine that is pivotal for the pathogenesis of many autoimmune diseases; it induces the differentiation of Th0 cells to Th2 cells." (PMID 28511637, 2017). "Th1 cytokines (IFNγ and IL12) are believed to play an important role in the induction of cell-mediated autoimmune disease whereas Th2 cytokines (IL4) promote primarily antibody-mediated autoimmune disease." (PMID 25614713, 2014). "The model we are using for this study represents a model of an organ-specific autoimmune disease associated with a TH2 phenotype, in which IL-4 promotes the disease and IFN-γ limits it." (PMID 24586934, 2014). "IL-4 has several characteristics that made it a good choice for using in cancer gene therapy, controlling inflammatory diseases, and studies on autoimmune diseases." (PMID 23493491, 2011). "NKT cells are an integral component in the suppression of autoreactive T cells and the prevention of autoimmune diseases, due to their capacity to quickly release large amounts of interleukin 4 (IL-4), favoring Th2 responses." (PMID 20844745, 2010). "The role of IL-4 in autoimmune diseases is complex and context-dependent." (PMID 41009491, 2025). "Furthermore, IL-4 is known to influence Th1-type responses, including those involved in antigen-induced autoimmune diseases." (PMID 38921035, 2024). "The evaluated cytokines can be classified into three broad groups: the proinflammatory Th-1 cytokines: IL-2, IFN-γ, and TNF-α; the counterbalancing Th-2 cytokines: IL-4, IL-5, IL-10, and IL-13; and the Th-17 cytokine IL-17A, which is actively involved in several autoimmune diseases including MS." (PMID 38932415, 2024). "By releasing IL-4, Th2 cells can directly inhibit autoimmune diseases." (PMID 37794975, 2023).
autoimmune disease (continued). "The involvement of IL4 and IL13 gene polymorphisms in a number of autoimmune diseases prompted us to investigate their role along with HLA-DQ and DR genotypes in genetic susceptibility of T1DM in a completely different population (Kuwaiti Arab children) which has a high incidence rate of T1DM." (PMID 37090926, 2023). "Autoimmune diseases are also associated with Th2 CD4 T-cells, which are induced by IL-4." (PMID 36830745, 2023). "In addition, IL-4 plays a role in antitumor immunity and autoimmunity and has been used as a therapeutic for autoimmune diseases and cancer." (PMID 35155574, 2022). "In addition to allergic responses, basophils are critically involved in autoimmune diseases, cancer, tissue repair, and fibrosis by releasing cytokines such as IL-4 and IL-13 that can modulate Th2 and M2-type immune responses." (PMID 36613520, 2022). "Th2 cells could produce IL-4, which mainly participated in the humoral immunity in pathogenesis of autoimmune diseases." (PMID 36457713, 2022). "Furthermore, IL-4 can downregulate Th1-mediated IgG subclasses of autoantibodies to prevent the development of lupus-like autoimmune disease." (PMID 35733860, 2022). "In autoimmune diseases, Th2 cells have an inhibitory effect on inflammation, and can inhibit the differentiation of Th1 cells by secreting IL-4, thereby reducing a variety of inflammatory factors secreted by Th1 cells and inhibiting the corresponding immune response." (PMID 35006213, 2021). "This study constitutes strong evidence supporting the hypothesis that IL-4-based therapy can be clinically effective in autoimmune disorders." (PMID 34831223, 2021). "Although IL-4 can mediate protection by directly promoting Th2 cell response and suppressing Th1 and Th17 differentiation, it also promotes the production of IgE from B cells, which likely mediate autoimmune disease, at least in part." (PMID 33816637, 2021). "Th 1 cytokines, such as TNF-α and IFN-γ, are known to lead the progression of autoimmune diseases such as type 1 diabetes and multiple sclerosis (MS), while IL-4, IL-10, and IL-13 refer to Th 2 cytokines and inhibit the pro-inflammatory response and reduce damage." (PMID 34445510, 2021). "T helper 1 (Th1) anti-inflammatory cytokines IL-4 and IL-10 are involved in the maintenance of homeostasis and, in particular, in controlling pro- and anti-inflammatory cytokines involved in infectious, allergic and autoimmune diseases." (PMID 32879392, 2020). "However, the effect of IL-4 on basophils themselves, which are emerging as relevant players in allergic as well as autoimmune diseases, was only scarcely addressed so far." (PMID 29915306, 2018). "Although the molecular mechanism of IL-25 in autoimmune disease remains unknown, previous studies, as well as the data reported herein, show that IL-25 strongly induced type 2 cytokines, such as IL-4 and IL-1330, 31, which are potent CIA inhibitors." (PMID 27812008, 2016). "The role of IL-4-producing CD8+ T cells have been determined in several autoimmune disease." (PMID 27467597, 2016). "Understanding the specifics of this IL-4/IL-5 axis in regards to B cell function could provide new targets for the design of therapeutic strategies for patients with autoimmune disorders or other inflammatory conditions." (PMID 23940537, 2013). "For instance IL-4, the signature cytokine of CD4+ Th2 cells, is known to reduce the production of Th1 cytokines by RA synovium - and IL-4 has been used in vivo as a treatment for a number of experimental autoimmune diseases in animals, including collagen-induced arthritis (CIA)." (PMID 22866899, 2012). "Delivery of IL-4, basically, helps to excite a Th2 response and may be beneficial in those autoimmune diseases, whose development depends on the polarization of Th1 cells." (PMID 22685550, 2012). "In this regard, IL-4, a Th2-secreted anti-inflammatory cytokine, may help to prevent the development of Th1 related autoimmune diseases." (PMID 22685550, 2012).